CXCL16 (C-X-C motif chemokine ligand 16)
Diseases named in the same sentence as CXCL16 in open-access papers (continued):
Sharing a sentence is not in itself a finding about the gene and the disease.
multiple sclerosis (12 papers, 2013 to 2025). A progressive autoimmune disorder affecting the central nervous system resulting in demyelination. "For example, in the setting of multiple sclerosis CXCL16 has been linked with neuropathology; yet it has also been shown to possess neuroprotective properties in the setting of stroke and in vitro excitotoxicity studies." (PMID 32804078, 2020). "It is also interesting to note that CXCL16 is a chemokine which has recently been associated with disease activity in multiple sclerosis and mouse models of experimental autoimmune encephalomyelitis." (PMID 25290448, 2014). "Similarly, CXCL16 blockade reduced serum IFNγ levels and in vitro antigen recall responses in a mouse model of multiple sclerosis." (PMID 27471636, 2016). "CXCL16 codes for a chemokine that is primarily expressed in lymphoid tissue, but also appears to have a protective effect on excitotoxic cell death in the brain and is induced in a mouse model of multiple sclerosis." (PMID 25905630, 2015).
glioblastoma (11 papers, 2017 to 2025). The most malignant astrocytic tumor (WHO grade IV). "The results indicated that the source of CCL5, CCL7, and CXCL1 in our experimental system was mainly MSCs, while CXCL16 was predominantly secreted by glioblastoma U251 cells." (PMID 39272976, 2024). "Our study is also the first to identify CXCR6+ T-cell subsets as being enriched in glioblastoma, as well as demonstrating CXCL16 expression in dissociated tumour biopsies and glioblastoma cell-lines." (PMID 35464424, 2022). "The CXCL16 expression present in a tumor is also present in endothelial cells, as shown in glioblastoma multiforme, meningioma, and non-small cell lung cancer." (PMID 33800554, 2021). "The effect of CXCL16 on microglia requires further research because in glioblastoma multiforme these cells have a very low expression of CXCR6 receptor." (PMID 33800554, 2021). "Along with other chemokines, CXCL16 is involved in the regulation of the cellular dormancy of glioblastoma multiforme cells after exposure to temozolomide (TMZ), a standard drug used in the treatment of this cancer." (PMID 33800554, 2021). "The chemokine CXCL16 is expressed in the brain, where it is neuroprotective against brain ischemia, and it has been found to be over-expressed in glioblastoma (GBM)." (PMID 30542347, 2018). "In this line, we observed that fast migrating glioblastoma cells show higher CXCL16 expression levels in comparison to slowly-migrating cells of the same tumors." (PMID 28698473, 2017). "Additionally, glioblastoma cells secrete C-X-C motif chemokine ligand 16 (CXCL16), which influences both TAMs and tumor cells through its receptor C-X-C motif chemokine receptor 6 (CXCR6)." (PMID 40427130, 2025). "CXCL16 pro-tumoral activity was suggested for glioblastoma (GBM) patient’s." (PMID 36686729, 2022). "Moreover, C-X-C motif chemokine ligand (CXCL) 16 (CXCL16) is secreted by glioblastoma cells, and by signaling through C-X-C motif chemokine receptor (CXCR) 6 (CXCR6) it polarizes TAMs towards the M2-like phenotype." (PMID 34503065, 2021). "Additionally, we did not observe any proliferative or anti-apoptotic effects in endogenously CXCL16-expressing glioblastoma cells." (PMID 28698473, 2017). "In this line, we could detect that fast migrating glioblastoma cells show higher CXCL16 expression levels in comparison to slowly-migrating cell fractions of the same tumor." (PMID 28698473, 2017). "In glioblastoma multiforme and meningioma, the microglia might also be a source of CXCL16." (PMID 33800554, 2021). "Interestingly, in brain tumors such as glioblastoma multiforme, CXCL16 is expressed in astrocytes." (PMID 33800554, 2021). "CXCL16/CXCR6 signaling can also act directly on tumor cells to promote their proliferation, migration and invasion in both human glioblastoma cells in vitro as well as in a glioma mouse model." (PMID 34503065, 2021). "Additionally, we could show that fast migrating glioblastoma cells isolated from freshly-dissected glioblastomas express CXCL16 at higher levels in comparison to slowly-migrating cells, giving a first hint that reverse signaling might also contribute to glioblastoma migration processes in vivo." (PMID 28698473, 2017). "To investigate a putative reverse signaling mediated by transmembrane CXCL16, we used CXCL16-positive and CXCR6-negative glioblastoma cell lines." (PMID 28698473, 2017). "In glioblastomas, CXCR6 is expressed by a small subset of tumor cells with stem cell properties, so that direct cell contacts might enable reverse signaling via CXCL16." (PMID 28698473, 2017). "To investigate a putative reverse signaling of transmembrane CXCL16 upon binding of its known receptor CXCR6, for the first approach, we used different CXCL16-positive, CXCR6-negative glioblastoma cell lines and stimulated them with 25 ng/mL recombinant CXCR6 for 10 or 15 min." (PMID 28698473, 2017).
glioblastoma (continued). "To investigate intracellular signaling of CXCL16 upon stimulation with CXCR6, initially, we used human glioblastoma cell lines (known to express transmembrane CXCL16, but not CXCR6) and applied CXCR6 in different forms." (PMID 28698473, 2017). "Next, we investigated the migratory potential of LOX-CXCL16 cells in comparison to LOX-pcDNA (control) and LOX-ΔCXCL16 (C-terminally truncated) and of T98G glioblastoma cells in a scratch assay with or without stimulation with recombinant CXCR6." (PMID 28698473, 2017).
myocardial infarction (11 papers, 2017 to 2025). Gross necrosis of the myocardium, as a result of interruption of the blood supply to the area, as in coronary thrombosis. "Increased baseline CXCL16 levels were associated with increased risk of myocardial infarction, further strengthening the case for CXCL16 as a prognostic biomarker for CAD." (PMID 33182772, 2020). "One study has shown that among patients with no previous incidence of coronary events, those with a high level of CXCL16 had twice the risk of heart attack (HA) exposure." (PMID 32676207, 2020). "For instance, in murine models of myocardial infarction, administration of anti-CXCL16 neutralizing antibodies inhibits monocyte infiltration and improve cardiac function after myocardial infarction." (PMID 40491927, 2025). "In the murine model of myocardial infarction, CXCL16-mediated activation of NF-κB and p38MAPK pathways drives upregulation of CCL4 and CCL5, resulting in amplified monocyte recruitment and subsequent aggravation of cardiac injury." (PMID 40491927, 2025). "In the case of CXCR6 (chemokine receptor for CXCL16), a recent publication has reviewed the contribution of chemokines and their receptors in myocardial infarction." (PMID 35625854, 2022). "Plasma CXCL16 levels were similarly elevated in myocardial infarction mice, as CXCL16 exerts a protective function by promoting macrophage phagocyte fragments." (PMID 35668739, 2021). "Additionally, CXCL16 has been shown to promote Ly6Chigh monocyte infiltration, exacerbating cardiac dysfunction following acute myocardial infarction." (PMID 41357074, 2025). "Meeting all the cutoff criteria across all the data set analyzed, MAN2A2/TNFRSF12A/SPP1/CSNK1D/PLAUR/PFKFB3/CXCL16 (herein we termed it MTSCPPC signature) was identified as a novel pathological signature of myocardial infarction and was used for subsequent analyses." (PMID 35163208, 2022). "A large cohort study of healthy individuals performed in Norway compared baseline CXCL16 levels between those who developed myocardial infarction and those who did not over the trial period of 11 years." (PMID 33182772, 2020).
diabetes (10 papers, 2011 to 2024). "CXCL16 plays an important role in leukocyte recruitment and inflammation and has been implicated in autoimmune and inflammatory diseases, including diabetes." (PMID 35235351, 2022). "While initial studies on CXCL16 in diabetes focused on diabetic nephropathy, recent work has implicated a role for CXCL16 in DR." (PMID 35235351, 2022). "This association was evidenced by multiple stepwise regression analysis of variables that were independently associated with serum levels of CXCL16 including decreased eGFR, diabetes mellitus, hypertension, increased CRP and PTH levels." (PMID 33312065, 2020). "Elderly women with higher VLDL and glycemia typically had higher levels of circulating CXCL16; these high circulating levels have previously been associated with the development of plaque deposits, artery walls, and/or diabetes." (PMID 28293269, 2017). "The current study demonstrated for the first time that ADAM10/CXCL16/NF-κB mediated STZ-induced diabetes." (PMID 35335970, 2022). "Our results suggest that CXCL16 is involved in the pathogenesis of renal dysfunction in diabetes patients as supported by two novel findings." (PMID 24489966, 2014). "Taken together, these results indicate that serum CXCL16 levels are elevated in renal damage patient independently from diabetes." (PMID 24489966, 2014). "To explore the physiological and pathological characteristics of CXCL16 in subjects with diabetes and DN, we measured the serum CXCL16 levels in 120 Chinese subjects and analyzed its association with a cluster of metabolic parameters." (PMID 24489966, 2014). "Our primary aim in this study was to characterize the clinical manifestation of CXCL16 in conjunction with pathophysiologic measures in diabetes and DN and to explore the relationship between CXCL16 and renal injury in diabetes patients." (PMID 24489966, 2014). "First, serum CXCL16 levels were significantly increased in diabetes patients with renal disease when compared with healthy subjects." (PMID 24489966, 2014). "While much is known from animal-based studies, little is known about CXCL16 in human subjects, particularly in patients with diabetes mellitus." (PMID 24489966, 2014). "However, other researchers observed that serum CXCL16 levels were negatively correlated with the 25(OH)D level in patients with type 2 diabetes mellitus (DM2)." (PMID 39062835, 2024). "Our data demonstrate that serum CXCL16 levels are significantly increased in subjects with DN, but not diabetes, and they are independently associated with renal function in DN." (PMID 24489966, 2014). "However, whether CXCL16 levels can be attributed to the onset and development of DN from the early stages of diabetes is still unclear." (PMID 24489966, 2014). "Since GDF15, endostatin, and CXCL16 are suggested to be biomarkers of CKD, our data suggest that VEGF-D may have a role as a biomarker in diabetic CKD." (PMID 35363168, 2022). "Results of the present study showed that hemodialysis patients with diabetes or hypertension had significantly higher CXCL16 levels compared to hemodialysis patients without diabetes or hypertension respectively." (PMID 33312065, 2020). "Our previous work showed that serum CXCL16 levels in DN were significantly higher than those of CKD patients without diabetes." (PMID 24489966, 2014). "We analyzed the mRNA expression of SRs (LOX-1, MSR1, CXCL16, CD36 and CL-P1) and macrophage markers (CD68, CD11c and CD206) in EAT from 45 patients with IHD (23 with type 2 diabetes mellitus (T2DM) and 22 without T2DM) and 23 controls without IHD or T2DM." (PMID 30894181, 2019).
Obesity (10 papers, 2012 to 2025). Accumulation of substantial excess body fat. "A recent study investigating the influence of obesity on IDD has identified CXCL16 as a potential diagnostic biomarker for both obesity and IDD, highlighting its role in regulating fatty acid metabolism and facilitating IDD progression." (PMID 40129665, 2025). "We identified CXCL16 as a diagnostic biomarker for obesity and IDD in this study by machine learning methods." (PMID 38044363, 2023). "In this study, a common diagnostic biomarker for IDD and obesity, CXCL16, was identified with machine learning algorithms, and the potential mechanism of CXCL16 action was explored by GSVA." (PMID 38044363, 2023). "Obesity was associated with an elevated expression of CXCL16 on monocytes that promoted the phagocytosis of oxLDL by scavenger receptor function of CXCL16." (PMID 35784287, 2022). "Previous studies have indicated an association between CXCL16 and obesity in C57BL6 mice and coronary comorbidities in humans." (PMID 28293269, 2017). "In the future, we intend to focus on elucidating the mechanisms by which inflammatory factors IL‐1β and CXCL16 contribute to the development of obesity in HFD‐KI mice." (PMID 38145352, 2024). "We found that the levels of IL‐1β and CXCL16 were upregulated in the mammary glands of mice at the pre‐obesity stage." (PMID 38145352, 2024). "The same results for CXCL16 were verified in an independent obesity validation dataset, GSE59034, and an independent IDD validation dataset, GSE124272." (PMID 38044363, 2023). "In obesity, the GO functions of the CXCL16 low-expression group were enriched in the regulation of macrophage fusion and chitin metabolic processes." (PMID 38044363, 2023). "Ultimately, we determined that C-X-C motif chemokine ligand 16 (CXCL16) was the best diagnostic biomarker for the development of IDD and obesity by Venn analysis." (PMID 38044363, 2023). "Differential expression analysis showed that CXCL16 was significantly overexpressed in obesity and significantly underexpressed in IDD." (PMID 38044363, 2023). "In conclusion, a common diagnostic biomarker for obesity and IDD, CXCL16, was identified using a machine learning algorithm." (PMID 38044363, 2023). "To summarize, the activated inflammatory microenvironment, such as increased expression of IL‐1β and CXCL16, may promote obesity in LINK‐A overexpressing mice under HFD by affecting adipocyte thermogenesis." (PMID 38145352, 2024). "The KEGG pathways of the CXCL16 high-expression group were mainly enriched in linoleic acid metabolism and fatty acid metabolism, and in the CXCL16 low-expression group of obesity, the pathways were mainly enriched in other glycan degradation and toll-like receptor signalling pathways." (PMID 38044363, 2023). "A relationship has been proposed between obesity and CXCL16." (PMID 33306334, 2021). "Obesity was also associated with increased expressions of angiogenesis-related proteins, in particular, angiogenin, endoglin, endostatin, endothelin-1, IGFBP-3, leptin, MMP-3, PAI-1, TIMP-4, CXCL16, platelet factor 4, DPPIV and coagulation factor III." (PMID 22748184, 2012). "Thus, the aim of the present study was to investigate the association between CXCL-16, BMP-2, and IL-17 plasma levels and overweight and obese conditions in middle-aged (35 to 55 years of age) and elderly (>60 years old) women to find possible targets to monitor early progression to obesity." (PMID 28293269, 2017). "This study provides evidence that CXCL-16, IL-17, and BMP-2 are potential plasma indicators of inflammatory status in middle-aged and elderly women; therefore, further investigation of obesity-related comorbidities is recommended." (PMID 28293269, 2017). "To clarify the sequence of inflammatory factor expression and obesity, we examined the expression of IL‐1β and CXCL16 in mammary tissue of mice after 1 week of HFD before the notable difference in body weight became evident." (PMID 38145352, 2024).
Obesity (continued). "Not much has been reported about the role of IL‐1β and CXCL16 in regulating the thermogenic effects in obesity." (PMID 38145352, 2024). "Luminex analysis showed that in the HFD-induced obesity mouse model, there was an obvious increase in serum proinflammation cytokines such as TNF-α, MCP-1, IL-12, IL-1β, IL-6, CCL3, CXCL16, and Resistin, which were further alleviated significantly in the CD226KO group." (PMID 34823548, 2021). "The role of FCER1 G, TYROBP, CXCL16 and FCGR2A in obesity has been discussed previously." (PMID 32684073, 2020). "However, this study only showed the correlation of CXCL16 in the effects of IDD and obesity, and whether CXCL16 mediates the development of IDD in obese patients needs to be further investigated." (PMID 38044363, 2023).
psoriasis (10 papers, 2020 to 2025). An autoimmune condition characterized by red, well-delineated plaques with silvery scales that are usually on the extensor surfaces and scalp. "Here we show that the metabolic disease state in psoriasis is associated with an upregulation of the chemokine and lipid receptor CXCL16 on monocytes of psoriatic patients and the activation of ILCs." (PMID 35784287, 2022). "CXCL16 expression was enhanced on all monocyte subsets in psoriatic patients compared with healthy controls and positively correlated with psoriasis activity and severity index, body mass index and the risk for cardiovascular disease indicated by PROCAM score." (PMID 35784287, 2022). "In order to understand innate immune mechanisms mediating this inflammatory pattern we investigated expression of the chemokine and lipid scavenger receptor CXCL16 in patients with psoriasis and associated comorbidities." (PMID 35784287, 2022). "Subsequently, to determine whether CXCL16 expression levels were causally regulated by pyroptosis induction, we treated psoriasis-derived MDMs with the pyroptosis-specific inhibitor VX-765 for 48 h and quantified CXCL16 gene expression." (PMID 40722833, 2025). "Interestingly, a high expression of CXCL16 on monocytes was associated with a stronger uptake of oxLDL which might have implications for the evolution of systemic disease manifestations in psoriasis." (PMID 35784287, 2022). "In conclusion, SBM alleviates the psoriasis-like phenotype by inhibiting the IL-23/Th17 axis and CXCL16-mediated endothelial activation." (PMID 38429819, 2024). "In particular, the expression of CXCL16 on classical monocytes was increased threefold compared with controls (mean MFI CXCL16 healthy: 8.6; mean MFI CXCL16 psoriasis: 23.9)." (PMID 35784287, 2022). "Together these data link a strong expression of CXCL16 to metabolic syndrome in psoriasis and indicate a possible link to ILC activation and tissue distribution in obese psoriatic patients." (PMID 35784287, 2022). "This study integrates multi-omics approaches to reveal the pyroptotic characteristics of psoriasis lesions and suggests that highly pyroptotic MDMs may participate in psoriasis pathogenesis through the CXCL16/CXCR6 signaling axis." (PMID 40722833, 2025). "Collectively, these findings suggest that CXCL16 may be a central molecule driving the inflammatory output of high pyroptotic MDMs in psoriasis." (PMID 40722833, 2025). "This study not only elucidates the functional coupling mechanism between the pyroptosis characteristic of MDMs and the CXCL pathway but also provides a novel theoretical basis and potential therapeutic target for psoriasis treatment by targeting the pyroptosis-CXCL16 axis." (PMID 40722833, 2025). "CXCL16 is overexpressed in the skin lesions of psoriasis patients." (PMID 37160878, 2023). "Interestingly, the intensity of CXCL16 expression on all monocytes and the monocytes subsets correlated significantly with the skin involvement scored by psoriasis activity and severity index (PASI)." (PMID 35784287, 2022). "Importantly, the epidermal basal cells in cluster 8 of KO samples were also enriched with the expression of inflammatory cytokines and chemokines, including Tslp, Il1f9 (IL-36γ), and Cxcl16, all of which have been demonstrated to contribute to the pathogenesis of psoriasis." (PMID 37809094, 2023). "The co-network indicated that CXCL16 positively correlated with TLR7 expression and was involved in the psoriasis process." (PMID 37160878, 2023). "In all three psoriasis mouse models, neutrophil number and immunofluorescence (CD11b and CD44) and CXCL16 expression were increased to different degrees in the IMQ + PBS group as compared to the NC group." (PMID 37160878, 2023). "IL17, IL-23, CXCL16 and CXCL17 was also significantly decreased by laboratory tests, suggesting that guselkumab has a good efficacy in the psoriasis treatment." (PMID 35693833, 2022).